REX1BD (required for excision 1-B domain containing)
Synonyms: C19orf60; FLJ20850; FLJ30108; FLJ34606; FLJ37391
Tractability: No criterion of Open Targets' tractability assessment is met for any kind of drug.
Gene: Protein-coding gene on chromosome 19 (18,588,685 to 18,592,338, forward strand). Ensembl gene ENSG00000006015.
Subcellular location (Human Protein Atlas): Vesicles
Gene Ontology:
Molecular function: protein binding
Genetic constraint (gnomAD): Loss-of-function variants: 22 observed, 15.86 expected, observed/expected ratio (o/e) 1.39, 90% interval 0.99 to 1.86. The synonymous counts are far from expectation, so gnomAD's model fits this gene poorly and the ratio says little. Missense variants: 293 observed, 220.34 expected, observed/expected ratio (o/e) 1.33, 90% interval 1.21 to 1.47. Synonymous variants: 146 observed, 92.64 expected, observed/expected ratio (o/e) 1.58, 90% interval 1.38 to 1.81.
Homologues: Orthologues: chimpanzee REX1BD (98% identical), pig REX1BD (78% identical), mouse Rex1bd (60% identical), dog REX1BD (54% identical), rat Rex1bd (44% identical).
Diseases named in the same sentence as REX1BD in open-access papers:
REX1BD is named in the same sentence as 2 diseases in open-access papers, as found by Europe PMC text mining. Sharing a sentence is not in itself a finding about the gene and the disease. The quoted sentences say what the papers report.
colorectal cancer (1 paper, 2021). A primary or metastatic malignant neoplasm that affects the colon or rectum. "FOXI2 is a forkhead binding gene associated with transcriptional activation which has been seen to be consistently hypomethylated in colorectal cancer and REX1BD (required for excision 1 binding domain) is a putative DNA repair gene." (PMID 33632293, 2021).
REX1BD also shares sentences with these, for which no sentence is quoted: diabetes (1 paper).